ULK1 (unc-51 like autophagy activating kinase 1)
Diseases named in the same sentence as ULK1 in open-access papers (continued):
Sharing a sentence is not in itself a finding about the gene and the disease.
pancreatic cancer (continued). "Furthermore, high phosphorylation levels of ULK1 at S405 and S415 were observed in human pancreatic cancer cell lines, all of which are known to exhibit high levels of autophagy." (PMID 33654220, 2021). "Interestingly, high phosphorylation levels of ULK1 S405 and S415 were observed in several human pancreatic cancer cell lines, all of which are known to have high levels of autophagy flux." (PMID 33654220, 2021). "However, the genetic or pharmacological blockade of either ULK1 or ASCT2 in NEDD4L-depleted cells sensitized pancreatic cancer cells, particularly in response to nutrient deprivation." (PMID 31959741, 2020). "Here, we show that NEDD4L, an E3 ubiquitin ligase, binds ULK1 in pancreatic cancer cells." (PMID 31959741, 2020). "Inhibition of PI4KB S256 and T263 phosphorylation led to a reduction in RINCAA activity and tumor growth in both xenograft and KPC models of pancreatic cancer, suggesting that targeting ULK1-mediated PI4KB phosphorylation could represent a promising therapeutic strategy for RAS-mutated cancers." (PMID 40055523, 2025). "Interestingly, the levels of phosphorylation of endogenous ULK1 at both S405 and S415 in the same pancreatic cancer cell lines were significantly higher than those in normal human pancreatic ductal epithelial cells and human pancreatic nestin-expressing (HPNE) cells." (PMID 33654220, 2021). "Ubiquitination by NEDD4-like E3 ligase (NEDD4L) in pancreatic cancer cells promoted ULK1 degradation, while NEDD4L depletion activated autophagy by stabilizing ULK1, which in turn supported cancer progression and survival." (PMID 34502089, 2021). "The functional significance of ULK1 in tumor progression is further supported by our findings that ULK1 depletion in both mouse (KPC) and human (MIA PaCa-2) pancreatic cancer cells significantly impaired their proliferation and invasion, supporting its role in tumor aggressiveness." (PMID 41408407, 2025). "However, multi-IHC revealed elevated ULK1 protein levels and activity, marked by phosphorylated ATG14 (pATG14), particularly in high-grade (grade 3) pancreatic tumors compared with normal tissues." (PMID 41408407, 2025). "Further, NEDD4L was found to inhibit ULK1- and ASCT2-mediated mitophagy whereby suppressing adequate fuel supplementation via mitochondrial metabolism, leading to inducing cell death and inhibiting tumor growth in pancreatic cancer cells." (PMID 36918822, 2023). "Therefore, these overall results support the critical role of NEDD4L in deregulating the protein stability of ULK1 and ASCT2, thereby effectively diminishing autophagy and further repressing pancreatic cancer growth." (PMID 31959741, 2020).
colon cancer (19 papers, 2015 to 2025). "To dissect the effects of autophagy essential genes AMPK and ULK1, we measured cell viability in three colon cancer cell line." (PMID 31871431, 2019). "The results of crystal violet and Hoechst33342 staining also show similar effects of knocking down AMPK or ULK1 in colon cancer cells." (PMID 31871431, 2019). "In this present study, our results show that NVP-BEZ235 induced autophagy through AMPK/ULK1 pathway in colon cancer cells." (PMID 31871431, 2019). "In a word, these results together suggest that NVP-BEZ235 induced autophagy through the AMPK/ULK1 pathway in colon cancer." (PMID 31871431, 2019). "Interestingly, suppression of SIRT1 by CF-EOs enhanced the acetylation of ULK1, which in turn prompted ROS-dependent autophagy in colon cancer cells." (PMID 38539819, 2024). "Additionally, for LoVo colon cancer cells, irinotecan inhibits mTOR and activates the autophagy-related genes, ULK1, ATG13, ATG4L, and AMBRA1, promoting autophagy with increased numbers of lysosomes and lysosomal activity, which contribute to irinotecan resistance." (PMID 39456585, 2024). "In colon cancer models, cafestol activated LKB1/AMPK/ULK1-dependent autophagy, leading to tumor suppression." (PMID 41373971, 2025). "Our immunoblotting results suggest that polydatin stimulates autophagy-related proteins, including phosphorylated ULK1, BECN1, ATG5, and LC3B, and has a protective effect against colon cancer." (PMID 34573109, 2021). "Treatment of HCT116 ATG16L1 T300 colon cancer cells with AR12 or neratinib increased the activities of the AMPK, ULK1 and ATG13." (PMID 34252884, 2021). "FuSiOn identified ten kinases (BMP2K, DCLK3, LIMK2, MAP2K5/MEK5, MAP3K3/MEKK3, ROS1, SIK2, TAOK2, ULK1, and ULK2) whose depletion mimicked the phenotypic effect of p62 depletion in HCT116 colon cancer cells." (PMID 33101709, 2020). "So targeting autophagy by knocking down AMPK/ULK1 or by combinational treatment with CQ markedly enhanced the effect of NVP-BEZ235 on tumor growth suppression both in vitro and in vivo, which may provide a critical insight into colon cancer therapy." (PMID 31871431, 2019).
diabetes (19 papers, 2015 to 2025). "Another basic research, through in vivo and in vitro experiments, revealed that asprosin alleviates diabetes-induced myocardial fibrosis by suppressing excessive autophagy mediated by the AMPK/mTOR/ULK1 pathway." (PMID 41458540, 2025). "Here, we detected diabetes-induced expression of Bnip3 with a further increase by exercise intervention in both wildtype and Ulk1-S555A mice." (PMID 38203804, 2024). "We subjected Ulk1-S555A KI mice and the wildtype littermates to the same diabetes and exercise protocol." (PMID 38203804, 2024). "In particular, current researches declared that the regulation ATG1/ULK1 by mTOR and AMPK pathway were associated with kidney disease pathogenesis in diverse conditions, such as acute kidney disease (AKI) and diabetes mellitus." (PMID 36081940, 2022). "Here, we employed a mouse model of diabetes to test the hypothesis that endurance exercise training mitigates diastolic dysfunction by promoting cardiac mitophagy (the clearance of mitochondria via autophagy) via S555 phosphorylation of Ulk1." (PMID 38203804, 2024). "Our findings suggest that endurance exercise training is highly efficacious in mitigating diastolic dysfunction and associated pathological changes in mice with severe diabetes, and that the exercise benefits are not dependent on S555 phosphorylation (activation) of Ulk1." (PMID 38203804, 2024). "To dissect the molecular mechanism of the benefits of exercise, we generated Ulk1-S555A knock-in mice and subjected these mice to the same diabetes condition with/without exercise interventions." (PMID 38203804, 2024). "We conclude that endurance exercise training mitigates diabetes-induced diastolic dysfunction independent of Ulk1 phosphorylation at S555." (PMID 38203804, 2024). "Voluntary wheel running mitigated diastolic dysfunction in both the wildtype and knock-in groups, indicating that phosphorylated Ulk1 at S555 is not required for exercise-mediated protection against diastolic dysfunction in this mouse model of diabetes." (PMID 38203804, 2024). "At both time-points, the kidneys of vehicle-injected diabetic mice had higher ratio of p-mTOR to mTOR, increased abundance of p62, lower abundance of ULK1 and Atg12, and reduced ratio of LC3B to LC3A compared to non-diabetic animals, consistent with diabetes-associated suppression of autophagy." (PMID 38443965, 2024). "Metformin is used in diabetes mellitus; it is thought to trigger AMPK upstream of the Becn1/Ulk1/Vps34 complex, though it has additional metabolic effects that may impact stem cells and contribute to its documented capacity to improve survival of ovarian cancer patients." (PMID 26418751, 2015). "In the baseline condition (without diabetes and hypertrophy), our results showed that EDL muscle exhibited greater autophagy, as indicated by the upregulation of phospho‐ULK1, Beclin‐1, and p62 proteins." (PMID 37470707, 2023).
non-small cell lung carcinoma (19 papers, 2015 to 2026). A group of at least three distinct histological types of lung cancer, including non-small cell squamous cell carcinoma, adenocarcinoma, and large cell carcinoma. "Phosphorylation of ULK1 on Ser757 (autophagy-inhibitory site) is associated with shorter overall survival in non-small cell lung cancer patients." (PMID 35365653, 2022). "ULK1 was recently linked to the metastasis of several types of tumors, such as non-small-cell lung cancer, esophageal squamous cell carcinoma, and breast cancer." (PMID 31913283, 2020). "This is consistent with recent studies reporting autophagy promotion upon cycloastragenol treatment through the AMPK/ULK1/mTOR pathway in human non-small-cell lung cancer lines or via Notch1 signaling in human keratinocytes." (PMID 41596421, 2026). "For instance, Claudin1 has been shown to induce drug resistance mediated by autophagy in non-small cell lung cancer by ULK1 phosphorylation, and it acts as an autophagy stimulant, accelerating the degradation of SQSTM1/p62." (PMID 37303041, 2023). "The upregulation of ULK1 in some cancer tissues has been reported, and the knockdown or the selective inhibition of ULK1 resulted in cell apoptosis in non-small cell lung cancer (NSCLC) cells." (PMID 34199860, 2021). "The phosphorylation of ULK1 on Ser757 inactivates ULK1, and is correlated with poor survival in non-small-cell lung cancer patients." (PMID 31913283, 2020). "Another example proposed that the knockdown of HOTAIR inhibits ULK1 phosphorylation-mediated autophagy to refrain drug resistance of non-small cell lung cancer cells." (PMID 32760216, 2020). "Similar to the results obtained with the VPS34-inhibitor SAR405, the ULK1-inhibitor SBI-0206965 synergizes with mTOR inhibition to induce cell death in A549 non-small cell lung cancer cells." (PMID 26390974, 2015). "Furthermore, CLDN1 activates autophagy and promotes resistance to cisplatin in non-small-cell lung cancer cells by upregulating Unc-51-like kinase 1 (ULK1) phosphorylation." (PMID 39457456, 2024). "Besides, the abnormal activation of ULK1 in non-small cell lung cancer can affect the skeletal dynamics of cancer cells and release related cell movement effectors, leading to distant metastasis." (PMID 34636718, 2021). "Inhibiting ULK1 has shown promise in sensitizing CSCs to chemotherapy, as evidenced by the ULK1 inhibitor SBI-0206965, which, in combination with mTOR inhibitor, increases cisplatin sensitivity in non-small cell lung cancer." (PMID 39456967, 2024). "Cell lysates of pancreatic ductal adenocarcinoma (PDAC) cell lines BXPC3 and 8988T had significantly higher phosphatase activity towards ULK1 S637 site compared with control cancer cell lines U2OS (osteosarcoma) and H460 (non-small cell lung cancer) that are not ‘addicted' to autophagy." (PMID 26310906, 2015).
cardiac hypertrophy (17 papers, 2020 to 2025). "Irisin prevents overloading-caused cardiac hypertrophy mainly via triggering defensive autophagy by stimulating Adenosine Monophosphate Activated Protein Kinase (AMPK)-Unc-51 like autophagy activating kinase 1 (ULK1) pathway." (PMID 36267573, 2022). "Is Ulk1/Rab9 associated autophagy able to regulate alternative mitophagy in other pathological conditions such as pressure overload induced cardiac hypertrophy, doxorubicin-induced myocardial remodeling, diabetic cardiomyopathy, and heat failure?" (PMID 35361231, 2022). "When the AMPK-ULK1 (Unc-51 Like Autophagy Activating Kinase 1) signaling pathway is activated by irisin, protective autophagy and autophagy flux can be induced to prevent cardiac hypertrophy caused by pressure overload and reduce the risk of high blood pressure." (PMID 36135450, 2022). "A publication in 2020 demonstrated that the ablation of miR-214 from renal proximal tubules prevented a decrease in ULK1 expression and autophagy impairment in diabetic kidneys, resulting in less renal hypertrophy and albuminuria." (PMID 38216907, 2024). "The inhibition of lncRNA-Gm15834 attenuates autophagy-mediated myocardial hypertrophy via the miR-30b-3p/ULK1 axis in mice." (PMID 36386240, 2022). "miR-26a-5p can also inhibit the autophagy in cardiac fibroblasts through targeting ULK1, which is critical for cardiac hypertrophy and heart failure." (PMID 31994603, 2020). "The first mechanism promotes cardiac hypertrophy via the miR‐30b‐3p/ULK1/autophagy pathway." (PMID 40032652, 2025). "Moreover, we found that the expression of other key autophagy-related genes such as ULK1, Atg12, and Atg4B, was significantly upregulated at the protein level in the left ventricle of rats with exercise-induced myocardial hypertrophy, whereas SQSTM1 (a marker of reduced autophagy) was downregulated." (PMID 32140172, 2020). "Previous studies also demonstrated that ULK1 and LC3B were activated during cardiac hypertrophy, and Beclin1 mediated autophagy was also enhanced during right ventricular remodeling, supporting our finding that ULK1, LC3B, and Beclin1 were up-regulated in physiological LVH." (PMID 32140172, 2020).
bladder cancer (16 papers, 2017 to 2025). "In bladder cancer, M2-like macrophage exosome-derived H19 could enhance ULK1 stabilization through alleviating the K48-linked polyubiquitination of ULK1, sequentially facilitating the autophagy of bladder cancer cell." (PMID 37637063, 2023). "Long non-coding RNA H19 from the exosomes of M2 tumor-associated macrophages inhibits the interaction between ULK1 and its specific E3 ubiquitin ligase NEDD4L, stabilizing ULK1 expression and promoting autophagy in bladder cancer cells." (PMID 38027016, 2023). "lncRNA H19-silenced exosomes from TAMs led to a significant increase in the interaction between NEDD4L and ULK1, whereas lncRNA H19 overexpression suppressed the interactions between NEDD4L and ULK1 in bladder cancer cells." (PMID 37568787, 2023). "M2-secreted exosomal lncRNA H19 can facilitate the autophagy process of bladder cancer (BC) through stabilizing Unc-51-like autophagy activating kinase 1 (ULK1)." (PMID 36612282, 2022). "To explore the mechanism by which O-GlcNAcylation regulates the basal autophagy level in bladder cancer cells, we determined the phosphorylation of ULK1 and its upstream regulators, including AMPK and mTOR." (PMID 32174982, 2020). "In bladder cancer, long non-coding RNA H19 from the exosomes of M2 tumor-associated macrophages interfers K48-linked polyubiquitination of ULK1 mediated by NEDD4L, stabilizing ULK1 expression and promoting bladder cancer cell autophagy." (PMID 38027016, 2023). "This study extends our understanding of the regulatory mechanism of ULK1 and suggests that H19 in tumor microenvironment could be a potential target for bladder cancer treatment." (PMID 35607322, 2022). "In summary, the major novelty in this study is that Vitamin K2 is able to induce autophagic cell death in bladder cancer cells by establishing the metabolic signal axis: PI3K/AKT/HIF-1α dependent glycolysis promotion-metabolic stress-AMPK/ULK1 activation-mTORC1 pathway suppression." (PMID 32382009, 2020). "We observed the activation of ULK1 and its upstream kinase AMPK in O-GlcNAc depletion in bladder cancer cells." (PMID 32174982, 2020). "It was reported that LncRNA H19 derived from TAMs could stabilize ULK1 expression by increasing the expression of LC3-II/I and decreasing SQSTM1/p62 levels, thereby activating bladder cancer cell autophagy." (PMID 39394189, 2024). "Our results exhibited that OA suppressed p-mTOR (Ser2448) and increased the levels of p-AMPKα (Thr172) and p-ULK1 (Ser317), indicating that AMPK-mTOR-ULK1 pathway might take part in OA-induced autophagy in bladder cancer cells." (PMID 28978086, 2017).
osteosarcoma (16 papers, 2015 to 2025). A usually aggressive malignant bone-forming mesenchymal neoplasm, predominantly affecting adolescents and young adults. "In osteosarcoma, ULK1 expression is elevated in tumor tissues of patients with osteosarcoma compared to adjacent normal tissues." (PMID 40883962, 2025). "In this study, we investigated the clinical and pathological significance of USP10 and Unc-51-like autophagy activating kinase 1 (ULK1) in osteosarcoma (OS), as well as the mechanism of USP10 action in ULK1-mediated autophagy and disease progression." (PMID 39218913, 2024). "Mechanistically, we observed that ebastine treatment triggered proapoptotic autophagy by activating AMPK/ULK1 signaling in osteosarcoma cells." (PMID 36632464, 2023). "To further determine how ebastine regulates the AMPK/ULK1 pathway in osteosarcoma, we analyzed the RNA-seq data and searched relevant reports." (PMID 36632464, 2023). "Another study also showed that SNHG6 inhibits autophagy and apoptosis but promotes metastasis in osteosarcoma via the miR-26a-5p/ULK1 axis." (PMID 35837104, 2022). "Another report shows AURKB knockdown resulted in a reduction in migratory and invasive ability of osteosarcoma cell line by through mTOR/ULK1 pathway." (PMID 35332150, 2022). "Knockdown of Aurora B promoted autophagy by decreasing mTOR/ULK1, and thereby suppressing osteosarcoma metastasis." (PMID 34585646, 2021). "In summary, we have newly identified the SNHG6/miR-26a-5p/ULK1 regulatory mechanism of autophagy in human osteosarcoma, and provided an optional choose for human OS treatment in the future." (PMID 30988663, 2019). "Overexpression of ULK1 promotes cell proliferation and mobility of osteosarcoma cells." (PMID 40883962, 2025). "For this purpose, we first treated OS921 osteosarcoma cells for 16 h with 5.8 μM etoposide simultaneously with either 25 μM CQ or 3 μM MRT68921, an early-stage autophagy inhibitor by suppressing ULK1, in contrast to CQ that blocks the late stage." (PMID 41365861, 2025). "We provide experimental evidence demonstrating that ebastine has antitumor activity in osteosarcoma and promotes autophagy by activating the AMPK/ULK1 signaling pathway, which is IPMK dependent." (PMID 36632464, 2023). "Furthermore, catalytically active USP1-mediated ULK1 stabilization contributes to the regulation of autophagy in cancer, and canonical autophagic flux is impaired in USP1-depleted cells through degradation of ULK1, followed by the inhibition of osteosarcoma cell growth." (PMID 36153316, 2022).
triple-negative breast carcinoma (16 papers, 2019 to 2026). An invasive breast carcinoma which is negative for expression of estrogen receptor (ER), progesterone receptor (PR), and human epidermal growth factor receptor 2 (HER2). "The compound activates ULK1 and autophagy through apoptosis induction in triple-negative breast cancer." (PMID 37213283, 2023). "Aspergillus induces autophagy in triple-negative breast cancer cells through the AMPK/ULK1 signaling axis." (PMID 36120378, 2022). "LYN-1604 dihydrochloride, used to treat triple-negative breast cancer, is an effective ULK1 activator (EC50 = 18.94 nM)." (PMID 34820053, 2021). "Narciclasine, an Amaryllidaceae isocarbostyril compound, induces autophagy-dependent apoptosis in triple-negative breast cancer cells by regulating the AMPK/ULK1 axis." (PMID 31001120, 2019). "Regulating ULK1 to regulate autophagy/autophagy-related cell death (ACD) may be effective in the treatment of triple-negative breast cancer." (PMID 35592424, 2022). "For example, LYN-1604, as a novel activator of ULK1, obviously up-regulated ATF3 to induce autophagy in triple negative breast cancer." (PMID 32398095, 2020). "Besides, the ULK1 activator LYN-1604, which can induce autophagy-related cell death through the ULK complex, shows significant anticancer activity in triple-negative breast cancer." (PMID 33344463, 2020).